SMAD2 (SMAD family member 2)
Diseases named in the same sentence as SMAD2 in open-access papers (continued):
Sharing a sentence is not in itself a finding about the gene and the disease.
liver fibrosis (continued). "We finally explored the effects of GZFL on TGF-β1/Smad2/3 signaling and IFN-γ/STAT1 signaling in CCl4-induced mouse model of liver fibrosis by using western blot." (PMID 35387552, 2022). "Smad2 and Smad3, as downstream signaling factors of TGF-β1 signaling pathway, can activate HSCs and further promote the occurrence and development of liver fibrosis." (PMID 36276815, 2022). "Evidences have shown that TGF-β1/Smad2/3 signaling play a pro-fibrotic role, while IFN-γ/STAT1/Smad7 signaling pathway exhibit an anti-fibrotic role in liver fibrosis progression." (PMID 35387552, 2022). "The activation of TGF-β signaling decreases the bone morphogenetic protein and activin membrane-bound inhibitor (BAMBI), SMAD7, and increases the SMAD2/3/4 proteins, resulting in the excessive production of ECM and the progression of liver fibrosis." (PMID 35051234, 2022). "Glycyrrhizic acid can not only inhibit SMAD2 and SMAD3 pathways mediated by TGF-β1, but can also change the pathological morphology of the bile duct ligation model and prevent liver fibrosis." (PMID 35886594, 2022). "All these data indicated that GZFL was able to ameliorate liver fibrosis in vitro and in vivo though suppressing TGF-β1/Smad2/3 signaling pathway." (PMID 35387552, 2022). "TGF-βIR can phosphorylate SMAD2 and SMAD3, which suggests that phosphorylation of SMAD2 and SMAD3, is required for the smooth transmission of the TGF-β signaling pathway and thus its activation and accelerating the development of liver fibrosis." (PMID 36435779, 2022). "Coadministration of ADSCs and HGF on diabetic mice with liver fibrosis enhanced antifibrotic effects confirmed by the downregulation of Col I, α-SMA, TGF-β1, and Smad2, while Smad7 was upregulated." (PMID 36359733, 2022). "Our research proved that sTREM‐1 bound to the HSC membrane receptor Robo2 activating the downstream Smad2/3 and PI3K/Akt signalling pathways and clarified its role and mechanism for promoting liver fibrosis." (PMID 34750987, 2021). "For example, in liver fibrosis, the antifibrotic effects of propylene glycol alginate sodium sulfate involved the suppression of TGF-β1, Smad2, and Smad3." (PMID 33981353, 2021). "sTREM‐1 has synergistic effect with CCl4 on liver fibrosis via Robo2‐Smad2/3 and PI3K/Akt pathway, knocking down Robo2 or inhibiting Smad2/3 or PI3K/Akt significantly blocked the sTREM‐1‐induced HSC activation and liver fibrosis." (PMID 34750987, 2021). "In conclusion, sTREM‐1 acts as a new ligand of Robo2; the binding of sTREM‐1 to Robo2 initiates the activation of the downstream Smad2/3 and PI3K/Akt signalling pathways, thereby promoting HSC activation and liver fibrosis." (PMID 34750987, 2021). "Based on the consistent expression of total Smad2 and Smad3, levels of TGF-β1 and phosphorylated Smad2 and Smad3 were upregulated in the liver fibrosis model, but decreased in the drug group, and the differences were statistically significant." (PMID 33488687, 2020). "Phosphorylated Smad2 (p‐Smad2) and phosphorylated Smad3 (p‐Smad3) generated by TGF‐β1 lead to the activation of hepatic fibrosis." (PMID 32233073, 2020). "Here, we provide evidence that targeting Fstl1 inhibits the activation of HSCs and ameliorates CCl4-induced liver fibrosis in mice by modulating TGF-β1-miR29a-Fstl1 regulatory circuit and downstream Smad2/JNK signaling in activated HSCs." (PMID 32933544, 2020). "Translocation of both linker and C-terminally phosphorylated Smad2 (pSmad2L/C) to the nucleus cooperates with pSmad3L and Smad4 to enhance PAI-1 transcription and promote hepatic fibrosis." (PMID 31991602, 2020). "Our study disclosed the protective role miR-98 played in liver fibrosis by targeting HLF and regulating a novel HIF-1α/TGF-β/Smad2/3 signaling pathway." (PMID 32637414, 2020). "Our results collectively suggest that PSS prevents hepatic fibrosis by suppressing inflammation, promoting ECM decomposition and inactivating HSCs through the TGF‐β1/Smad2/3 and JAK2/STAT3 pathways." (PMID 32233073, 2020).
liver fibrosis (continued). "LIG prevents and alleviates the development of liver fibrosis by downregulating TGFβ1, TβRII, CCN2, and Smad2/3, and type I collagen while upregulating Smad7 and inhibits proliferation of hepatic stellate cells." (PMID 31886227, 2019). "In particular, the TGF-β1 SMAD2/3 pathway is significantly increased in CC14-induced mice as compared to normal mice, while the TGF-β1 inhibitor (SB431542) significantly attenuated liver fibrosis and TGF-β1 SMAD2/3." (PMID 31600917, 2019). "During liver fibrosis, Nogo-B inhibits hepatic stellate cell apoptosis and facilitates TGF-β-Smad2 pathway to mediate hepatic fibrosis." (PMID 29795235, 2018). "In conclusion, our current study demonstrated that Andro ameliorated liver fibrosis in part through suppressing the activation of the TLR4/NF-κB and TGF-β1/Smad2 signaling pathways." (PMID 29743985, 2018). "Ginseng extract had an anti‐fibrosis effect in a CCl4‐induced liver fibrosis model by regulating the TGF‐β1/Smad signaling pathway via the inhibition of Smad3, Smad2, and TGF‐β1 expression." (PMID 28086769, 2017). "TGF-β1 has been established as the crucial fibrogenic cytokine promoting liver fibrosis, due to its activation of HSCs via TGF-β1-induced phosphorylation of receptor-activated Smad2 and Smad3." (PMID 26788244, 2016). "TMP exerts anti-hepatic fibrosis effect through decreasing the expression of CTGF and Smad2/3, as well as inhibiting the proliferation of HSC-T6 cells." (PMID 26019625, 2015). "Suppression of Smad7 by DNA methyltransferase 1 promoted the phosphorylation of Smad2 and Smad3 that had been induced by HSC activation, or liver fibrosis in general." (PMID 25435153, 2015). "In this study, our results showed that TMP decreased the expression of Smad2/3 and CTGF, and inhibited the proliferation of HSC-T6 cells, through which TMP would exert its anti-hepatic fibrosis effects." (PMID 26019625, 2015). "Therefore, we verified the mRNA expression levels of the TGF-β/Smad2/SMAD3 pathway, liver fibrosis, and bile acid metabolism genes." (PMID 40453659, 2025). "For example, liver fibrosis can be influenced by serum exosome-derived miR-193a-5p and miR-381-3p through modulation of the AMPK/TGF-β/Smad2/3 signaling pathway, while lung cancer patients with significantly reduced levels of miRNA-508-3p tend to have poorer survival rates." (PMID 41317550, 2025). "Besides ID1, TGF-β1 also promotes the activities of several signaling pathways including Smad2/3, TAK1, JNK, p38, MAPKs, RhoA–ROCK, JAK–STAT3, and PI3K–AKT, which contribute to the induction of hepatic fibrosis." (PMID 39199400, 2024). "Our results collectively suggest that cVIM acts as a sponge for miR-122-5p and miR-9-5p to enhance expression of TGFBR1 and TGFBR2, leading to the phosphorylation of Smad2 (a downstream mediator of TGF-β signaling), which finally promotes TGF-β/Smad pathway and the progression of liver fibrosis." (PMID 38243118, 2024). "VLD attenuated hepatic fibrosis by MAPK/ERK1/2 (MEK1/2), ERK1/2, p38α, NF-κB and Smad2/3." (PMID 39359922, 2024). "KLF10 deletion resulted in an increased DEN-induced HCC burden with significant upregulation of SMAD2, although loss of KLF10 did not alter HFD-induced liver fibrosis." (PMID 37946098, 2023). "Furthermore, the OEFL and its main bioactive substance, p-coumaric acid, alleviated liver fibrosis by downregulating TGF-β, SMAD-2, SMAD-4, α-SMA, and upregulating MMP-1." (PMID 35208964, 2022). "The expression of TGF-β1, Smad2/3, p-Smad2/3, and Smad4 sharply increased as liver fibrosis progressed and peaked at 7 or 9 wpi, while the negative regulator Smad7 dramatically decreased at 9 wpi." (PMID 36474240, 2022). "The exact mechanism by which IFN-I interacts with TGF-β to cooperatively activate SMAD2/3 in HepSC is not clearly defined yet but will provide critical insights on how HIV-induced IFN-I contributes to liver fibrosis." (PMID 35639478, 2022).
liver fibrosis (continued). "MSC transplantation could alleviate liver fibrosis and reduce the expression of transforming growth factor-β1 (TGF-β1), Smad2, collagen type I, and α-SMA, and pathological examination showed reduced liver fibrosis areas." (PMID 34136500, 2021). "In conclusion, PSS prevents hepatic fibrosis by suppressing inflammation, promoting extracellular matrix (ECM) decomposition and inactivating hepatic stellate cells through mechanisms involving the TGF‐β1/Smad2/3 and JAK2/STAT3 pathways in vivo and in vitro." (PMID 32233073, 2020). "Myricetin also effectively inhibited the expression of TGFβ1, Smad2, phospho-Smad2, Smad3, phospho-Smad3, ERK, phospho-ERK, Akt, and phospho-Akt in the liver of infected mice, suggesting that myricetin attenuated liver fibrosis in mice via modulating TGFβ1 and Akt signaling." (PMID 32373112, 2020). "Therefore, it appears that miR-34 overexpression improves the development and progression of hepatic fibrosis by targeting SMAD4 and regulating the TGF-β1 SMAD2/3 pathway." (PMID 31600917, 2019). "However, this increase in TGFβ and Smad2/3 expression is offset by overexpression of Smad7, resulting in attenuation of TAA-induced liver fibrosis." (PMID 30509307, 2018). "As illustrated in figure seven, B19 NS1 protein aggravates the hepatic fibrosis by enhancing the expression of TGF-β isoforms and activation of Smad2/3, which urge phosphorylated Smad2/3 to cooperate with Smad4 and Sp1 and induce the consequent fiboriss-related proteins, including PAI-1 and α-SMA." (PMID 23840852, 2013). "Moreover, in a study investigating the alleviation of carbon tetrachloride-induced liver fibrosis in rats, PEA was shown to reduce the phosphorylation of Smad2 in TGF-β1-stimulated LX-2 hepatic stellate cells and significantly inhibit the transcriptional activity of Smad complexes." (PMID 40994978, 2025). "Although this study did not elucidate the interaction between the TGF-β1/Smad2/3 pathway and gut microbiota in liver fibrosis, we found that intervention with QgYp can reduce the levels of Lipopolysaccharide (LPS) in the liver, portal vein serum, and colon of rats." (PMID 39925848, 2025). "Notably, in the untreated group, the protein expression levels of pro-fibrotic mediators TGF-β, p-Smad2, and p-Smad3 were markedly elevated compared with the healthy group in the CCL4‐induced liver fibrosis model, consistent with the hyperactivation of this pathway during fibrosis progression." (PMID 40483470, 2025). "As DNMT plays an important role in DNA methylation, DNMT inhibition may block the hypermethylation and downregulate related genes (such as PTGIS, PTEN, and Smad2/Smad3), inhibit the activation and proliferation of HSCs, inhibit the expression of α-SMA and COL1A1 in vitro, and delay liver fibrosis." (PMID 37056286, 2023). "Smad2/Smad3, a downstream factor of Smad signaling, is considered a key regulator of TGF-β signaling in tissue fibrogenesis, and more importantly, Smad7 is a potential major transcriptional repressor of HSC activation and liver fibrosis in vitro and in vivo, regulating Smad2/Smad3 phosphorylation." (PMID 37056286, 2023). "A recent study reveals that the expression of C-myc and Smad2/3 are upregulated in LPS-treated hepatic stellate cells, while the expression of recombinant thrombospondin 1 and phosphorylation of STAT3 is upregulated in the hepatocytes of mice with liver fibrosis." (PMID 36986363, 2023). "Additionally, TGFβ has been known to increase ROS generation, which plays a crucial role in stimulating liver fibrosis As a negative-feedback regulator, Smad7 interferes with the interaction between TGFβ type I receptor and Smad2." (PMID 37446633, 2023). "Our study showed that myricetin suppressed the expression of TGFβ1, phospho-Smad2, phospho-Smad3, phosph-ERK1/2, Akt, phospho-Akt in schistosome-infected mice, revealing that myricetin may reduce liver fibrosis in schistosome-infected mice by inhibiting TGFβ1/Smad/ERK and PI3K/Akt signaling." (PMID 32373112, 2020).
liver fibrosis (continued). "However, our previous work presented that inhibition of Robo1 attenuated hepatic fibrosis through downregulation of the phosphorylation of both Smad2 and Smad3 in HSC independent of TGF-β1." (PMID 29743985, 2018). "Compared with the blank control group, the gene expression of Smad2 and Smad3 in the TGF-β1 experimental group was increased while Smad7 was decreased, indicating that TGF-β/Smad pathway may be involved in the process of excessive activation of HSC and hepatic fibrosis." (PMID 27990439, 2016). "In the context of liver fibrosis, Smad7 acts as a negative feedback regulator, inhibiting the TGF-β1/Smad signaling by preventing the binding of activated TβRI to Smad2/Smad3." (PMID 36474240, 2022). "In addition, miR-193 plays a protective role in pulmonary and hepatic fibrosis by regulating canonical TGF-β/SMAD2/3 and non-canonical TGF-β/PI3K/AKT/mTOR signaling pathways, respectively." (PMID 34381815, 2021).
renal fibrosis (177 papers, 2011 to 2026). A final common manifestation of a wide variety of chronic kidney diseases characterized by glomerulosclerosis and tubulointerstitial fibrosis. "In our study, we demonstrated that HRAS activated RREB1, enhancing SMAD2/3 association with Snai1 and Has2cis-regulatory regions during renal fibrosis." (PMID 39913299, 2025). "The positive correlation between Hcy and phosphorylated STAT3 ratio, as well as TGF-β1 and phosphorylated Smad2/3 ratio in renal fibrosis tissues, revealed the mechanisms of folate deficiency effects." (PMID 39919369, 2025). "A study on renal fibrosis suggested that inhibition or knockout of YAP downregulated the expression of SMAD2/3, mainly reducing the nuclear localization of SMAD2/3, thereby effectively alleviating renal fibrosis caused by UUO." (PMID 37118830, 2023). "AGEs/RAGE axis is capable of activating TGF-β1-independent Smad2/3 signaling through an ERK/p38/MAPK pathway to cause renal fibrosis and inflammation." (PMID 31262060, 2019). "Of interest is that conditional deletion of SMAD2 enhanced renal fibrosis, because SMAD2 deficiency induced excess phosphorylation of SMAD3, resulting in the SMAD3 binding to a collagen promotor and auto-induction of TGF-β." (PMID 30150520, 2018). "A pro-fibrotic effect with activation of Smad2/3 signals of the loss of TRPV1 was reported in a mouse model of deoxycorticosterone acetate-salt-induced renal fibrosis and dysfunction." (PMID 29971480, 2018). "The activation or inactivation of TGF-β/Smad signaling pathway, as reflected by the expression levels of Smad2, Smad3 and Smad7, is a pathogenic mechanism in the progression of renal fibrosis." (PMID 30101622, 2018). "TGF-β causes renal fibrosis via activation of Smad2 and Smad3 leading to complex formation with Smad425." (PMID 28743964, 2017). "Together, our data show that the human‐specific CHRFAM7A gene may be able to down‐regulate the TGF‐β1/Smad2/3 signalling pathway in the kidney, delaying the progression of renal fibrosis caused by obstructive injury." (PMID 36479618, 2023). "Smad2/3 signaling is closely associated with renal fibrosis." (PMID 37446016, 2023). "When released from LAP (latency-associated peptide) and LTBP (latent TGF-β-binding protein), active TGF-β1 binds with its type II receptor that activates type I receptor and downstream effectors, Smad2 and Smad3, to regulate genes associated with renal fibrosis." (PMID 31754396, 2019). "Cyanoglycosides significantly reduce the expression of renal fibrosis-related proteins (TGF-β/Smad2/Smad3)." (PMID 41466459, 2026). "An enhancement in Smad3 signaling and renal fibrosis were observed in mice with Smad2 conditional knockouts." (PMID 40141345, 2025). "Global SMAD2 deletion in the unilateral ureteral obstruction model exacerbates renal fibrosis, an effect attributed chiefly to altered signaling in tubular epithelial cells." (PMID 40895578, 2025). "Our results revealed that PP ameliorated renal fibrosis by upregulating the expression of Smad7 and inhibiting the activation of TGFβ‐Smad2/3 signal pathway in kidneys from db/db mice." (PMID 40688601, 2025). "Research targeting TGF-β1 and its associated Smad2/3 signaling pathway has demonstrated a reduction in the phosphorylation of Smad2/3, effectively inhibiting renal fibrosis." (PMID 40284165, 2025). "Our study found that E2 administration in AD-fed male mice significantly alleviated renal fibrosis and inflammation, primarily the inhibition of NF-κB and SMAD2/3 pathway activity." (PMID 39941126, 2025). "Previous reports have suggested that the TGF-β1/Smad2/Smad3 signaling pathway is involved in EMT-mediated renal fibrosis." (PMID 39451219, 2024). "A Klotho-derived peptide inhibits TGF-β1/Smad2/3/MAP kinase signaling and associated fibroblast activity to prevent renal fibrosis." (PMID 39765782, 2024).